MYCN (MYCN proto-oncogene, bHLH transcription factor)
Diseases named in the same sentence as MYCN in open-access papers (continued):
Sharing a sentence is not in itself a finding about the gene and the disease.
neuroblastoma (continued). "In a transgenic zebrafish cancer model, overexpression of MYCN resulted in the development of neuroblastoma with a penetrance of less than 20%." (PMID 24416389, 2014). "In another study, it was found that there was a reciprocal regulation between B-Myb and MYCN in neuroblastoma, and the tumor cells were addicted to B-Myb in a MYCN-dependent manner for cell proliferation." (PMID 25344919, 2014). "High-level amplification of the MYCN gene – besides a few other amplified genes – is detected in 20–25% of neuroblastomas." (PMID 25161957, 2014). "The co-amplification and co-expression of NCYM and MYCN in human primary neuroblastomas prompted us to investigate the functional interaction between NCYM and MYCN." (PMID 24391509, 2014). "The fast baseline tumor R2* measured in the Th-MYCN model is consistent with the aggregation of deoxygenated erythrocytes, described as blood lakes, and which are characteristic of childhood neuroblastoma." (PMID 24667968, 2014). "We have found that S(+)-ibuprofen destabilizes MYC and MYCN proteins in five well-characterized neuroblastoma cell lines." (PMID 24173829, 2014). "Overexpression of MYCN in human neuroblastoma cells induced NCYM mRNA expression, whereas shRNA-mediated knockdown of MYCN downregulated endogenous NCYM mRNA levels." (PMID 24391509, 2014). "Sunitinib significantly inhibited the growth of established, subcutaneous MYCN-amplified neuroblastoma xenografts in nude mice and demonstrated an anti-angiogenic effect in vivo with a reduction of tumor vasculature and a decrease of MYCN expression." (PMID 24759734, 2014). "Previous reports have suggested that neuroblastoma cell lines expressing high levels of MYCN were significantly more sensitive to mTOR inhibitors compared with cell lines expressing low MYCN levels." (PMID 24391509, 2014). "In neuroblastoma, MYCN amplification occurs in approximately 25% of neuroblastoma cases; MYCN oncogene activation through amplification is an important hallmark of advanced tumor stage and poor prognosis." (PMID 24459422, 2013). "In the Pediatric Oncology Group (POG) study of 850 children with localized neuroblastoma, only six had MYCN-amplified tumors; three remained disease free after surgical therapy, and three experienced recurrences." (PMID 24396620, 2013). "Both transcription factors are considered potential specific targets for cancer therapy and downregulation of MYCN expression by treatment with antisense or by retinoid acids decreases proliferation of neuroblastoma cells." (PMID 23702334, 2013). "Roughly 25% of most aggressive neuroblastomas are characterized by the amplification/overexpression of the MYCN transcription factor that nowadays is considered one of the most robust prognostic factors for the neuroblastoma unfavorable outcome." (PMID 23482921, 2013). "The recently demonstrated functional and synergistic relationship between MYCN and ALK, another important oncogene in neuroblastoma, further reinforces the central role of MYCN in neuroblastoma oncogenesis." (PMID 23308108, 2013). "We used shotgun LC/MS to compare phosphorylation between a human MYCN amplified neuroblastoma cell line (NB10), modeling a resistant tumor, and a human neural precursor cell line (NPC), modeling a normal baseline neural crest cell." (PMID 24349301, 2013). "MYCN, a critical oncogene in neuroblastoma, is amplified in approximately 25% of the cases and its amplification strongly correlates with poor outcomes in neuroblastoma patients." (PMID 23468863, 2013).
neuroblastoma (continued). "MYCN is a crucial driver gene in the childhood cancer neuroblastoma as illustrated by overexpression due to genomic amplification in a large subset of high risk tumors and formation of neuroblastoma in MYCN-driven transgenic mouse and zebrafish model systems." (PMID 23308108, 2013). "Mice were injected (i.v.)with folate-nanoliposome entrapped MYCN siRNA or control siRNA for 5 days and gene silencing effect of MYCN siRNA in LA-N-5 neuroblastoma were examined by real-time PCR and Western blot." (PMID 23806172, 2013). "Angiogenesis is also a key pathological marker in neuroblastoma and many works correlate its induction to the amplification and/or overexpression of MYCN transcription factor." (PMID 23482921, 2013). "A later study found that miR-184 was involved in a common genetic pathway through targeting the serine/threonine kinase AKT2 by acting with MYCN transcription factor to inhibit neuroblastoma cell survival." (PMID 23724109, 2013). "MYCN gene amplification (MNA) was one of the first genetic markers for highly aggressive neuroblastoma to be established, and remains a powerful prognostic indicator." (PMID 23656755, 2013). "Oral administration of I-BET726 to mouse xenograft models of human neuroblastoma results in tumor growth inhibition and down-regulation MYCN and BCL2 expression, suggesting a potential role for these genes in tumor growth." (PMID 24009722, 2013). "Oncogene MYCN is amplified and overexpressed in 25% of neuroblastoma patients, and correlates to poor outcomes in older children." (PMID 23468863, 2013). "Rutin is a potential therapeutic drug for the treatment of neuroblastoma, particularly in MYCN expression tumor." (PMID 24459422, 2013). "On the other hand, a significant amount of work has been done to better understand the importance of MYCN-mediated transcriptional repression in neuroblastoma." (PMID 23482921, 2013). "It is generally accepted that the amplification of the MYCN proto-oncogene is highly relevant to the genesis and prognosis of neuroblastoma." (PMID 23806172, 2013). "We then compared the expression profiles of a MYCN amplified primary neuroblastoma line (p202) treated with Nutlin-3a or its inactive enantiomer Nutlin-3b for 3, 8, and 16 hours." (PMID 24348903, 2013). "We describe an unusual case of adult neuroblastoma with MYCN amplification diagnosed incidentally and discuss possible therapeutic dilemmas." (PMID 24396620, 2013). "Further analyses of a large series of neuroblastoma tumors and cell lines (n = 223) revealed enrichment for known MYCN up regulated genes in focal gains and amplicons." (PMID 23308108, 2013). "This is a MYCN-dependent effect as confirmed by experiment in TET21N neuroblastoma cells that carry a MYCN conditional minigene." (PMID 23482921, 2013). "MYCN amplification occurs in approximately 20% of primary neuroblastoma tumors and strongly correlates with advanced stage disease and resistance to therapy." (PMID 24009722, 2013). "Neuroblastoma tumors that are of advanced Stage, MYCN amplified or that are diagnosed after 18 months of age carry the worst prognosis." (PMID 24130898, 2013). "MYCN is a well-known oncogene overexpressed in different human malignancies including neuroblastoma, rhabdomyosarcoma, medulloblastoma, astrocytoma, Wilms' tumor, and small cell lung cancer." (PMID 24396620, 2013). "We developed explicit rules, predicting the outcome of neuroblastoma patients on the bases of Age at diagnosis, MYCN amplification, INSS stage and NB-hypo signature." (PMID 23815266, 2013). "MYCN together with MYB were shown to be involved in a reciprocal regulatory loop promoting survival/proliferation of neuroblastoma cells." (PMID 23702334, 2013). "In this work we demonstrate that MYCN-amplified neuroblastoma cells contain elevated levels of multiple phosphopeptides from receptor tyrosine kinases capable of activating several downstream signaling pathways." (PMID 24349301, 2013).
neuroblastoma (continued). "Here, we identified high levels of phosphopeptides from downstream mediators of these pathways, including PI3K p85β, PDK1, GSK3β, MEK2, ERK1, and ERK2, in MYCN-amplified neuroblastoma cells." (PMID 24349301, 2013). "The growth effects observed following I-BET726 treatment were consistent with a loss of N-Myc activity, as targeted inhibition of MYCN expression was shown to trigger growth inhibition, differentiation, and apoptosis in neuroblastoma cell lines." (PMID 24009722, 2013). "MYCN knock-down in neuroblastoma MYCN-amplified (MNA) cell lines such as IMR32 and SKNBE(2c) determines an up- or down-regulation of several cell cycle related genes involved in different important signaling pathways." (PMID 23482921, 2013). "Here, we demonstrated elevation of phosphopeptides from Ret and its Shc3 substrate in a MYCN-amplified neuroblastoma cell line, suggesting activation of this pathway in these cells." (PMID 24349301, 2013). "This indicates that folate-nanoliposome entrapped MYCN siRNA treatment can lead to apoptosis of neuroblastoma in vivo." (PMID 23806172, 2013). "The expression of PPARδ1 and ALOX5 were examined across the following groups: stages 1 & 2, stage 3, stage 4, stage 4S and MYCN amplified neuroblastoma." (PMID 23874790, 2013). "Detection of the MYCN in circulating DNA occurs in the early progression of MYCN-amplified neuroblastomas." (PMID 24065096, 2013). "Recently, a MYCN signature was proposed in neuroblastoma based upon expression changes following knockdown of MYCN in the MYCN-amplified IMR32 cell line that also correlated with MYCN expression in neuroblastoma tumors." (PMID 24009722, 2013). "Our results demonstrate high levels of phosphopeptides from IGF-1R/IR, as well as its major substrates, IRS-2 and Shc, in MYCN-amplified neuroblastoma cells." (PMID 24349301, 2013). "A focal 5 kb gain encompassing the MYCN regulated miR-17∼92 cluster as sole gene was detected in a neuroblastoma cell line and further analyses of the array CGH data set demonstrated enrichment for other MYCN target genes in focal gains and amplifications." (PMID 23308108, 2013). "As for TRKA, the expression of NGFR is strongly down-regulated in aggressive neuroblastoma having MYCN overexpression." (PMID 23482921, 2013). "The overexpression of RET and the inhibition of MYCN oncogenes as markers of cell differentiation and the effect of RA as an inducer of cell differentiation in neuroblastoma cell cultures have been widely described." (PMID 23650528, 2013). "Enrichment analysis for (direct) MYCN target genes in focal aberrations in the clinico-genetic neuroblastoma tumor subgroups and cell lines." (PMID 23308108, 2013). "The mechanism linking low PPARδ1 and ALOX5 to MYCN amplification status in neuroblastoma needs to be investigated, and the study raises questions over the potential role of PPARδ1 in promoting cell survival signalling in neuroblastoma." (PMID 23874790, 2013). "The c-myc-immortalized neural crest progenitor-like cell line JoMa1 can be transformed to neuroblastoma-like cells upon substitution of its c-myc activity by MYCN." (PMID 23675538, 2013). "MYCN amplification and overexpression occur in about 25% of total neuroblastoma cases and this percentage increases at 30% in advanced stage neuroblastoma." (PMID 23482921, 2013). "Gene therapeutic effect of folate-nanoliposome entrapped MYCN siRNA was evaluated by TUNEL assay of neuroblastoma." (PMID 23806172, 2013). "Genetic analysis in neuroblastoma has identified the profound influence of MYCN amplification and 11q deletion in patients’ prognosis." (PMID 23341988, 2013). "So far, MYCN expression profile is still one of the most robust and significant prognostic markers for neuroblastoma outcome." (PMID 23482921, 2013). "Co-expression of BCL2 and MYCN in neuroblastoma cell lines increases tumorigenicity and protects cells from apoptosis." (PMID 24009722, 2013).
neuroblastoma (continued). "Bcl-2 is highly expressed in a significant percentage of primary neuroblastoma tumors (16-52%), and expression correlates with markers of poor prognosis including MYCN-amplification." (PMID 24009722, 2013). "Numerous studies in neuroblastoma have shown that MYCN can act as a transcriptional regulator factor even on miRNA expression." (PMID 23482921, 2013). "Recently it has been demonstrated that MYCN protein level is predictive for neuroblastoma outcome independently from its genomic amplification and up-regulation." (PMID 23482921, 2013). "Taken together, our work reveals high levels of IGF-1R/IR and Ret phosphopeptides, with associated high abundance of phosphopeptides from downstream mediators of the PI3K/Akt/mTor and Raf/MEK/ERK pathways in MYCN-amplified neuroblastoma." (PMID 24349301, 2013). "Curiously, this cells are MYCN amplified, suggesting that MAX expression is sufficient to revert proliferation even in more aggressive neuroblastoma cell variants." (PMID 24349289, 2013). "Since MYCN gene amplification plays a key role in the neuroblastoma progression, inhibition the MYCN gene expression becomes a probable strategy for high-risk neuroblastoma therapy." (PMID 23806172, 2013). "In vitro, RA induces growth arrest, down-regulation of MYCN expression and differentiation in neuroblastoma cells." (PMID 23874790, 2013). "Shotgun LC/MS was used to compare phosphorylation between a human MYCN amplified neuroblastoma cell line (NB10), modeling a resistant tumor, and a human neural precursor cell line (NPC), modeling a normal baseline neural crest cell." (PMID 24349301, 2013). "MYCN plays a central role in neuroblastoma invasiveness primarily by direct or indirect repression of specific target genes." (PMID 23482921, 2013). "Amplification of MYCN oncogene is an established marker indicating aggressive tumor progression of neuroblastoma (NBL)." (PMID 23320395, 2013). "This was not surprising as Gli1 overexpression induces differentiation of SH-SY5Y neuroblastoma cells and decreases the rate of mitosis in a number of MYCN-amplified neuroblastoma cell lines in vitro." (PMID 23900341, 2013). "Our data provides evidence, for the first time, that overexpression of Gli1 retards proliferation and reduces anchorage-independent growth of MYCN-amplified neuroblastoma cells." (PMID 23900341, 2013). "Since potent anti-proliferative activity was observed for BET inhibitors in MYC-driven hematologic cancer models, we screened a panel of neuroblastoma cell lines, in which MYCN amplification is common, for effects on cell growth following I-BET726 treatment." (PMID 24009722, 2013). "MYCN is a well-known oncogene over-expressed in different human malignancies including neuroblastoma (NB), rhabdomyosarcoma, medulloblastoma, astrocytoma, Wilms’ tumor, and small cell lung cancer." (PMID 23162796, 2012). "The levels of MYCN, a validated target of miR-34a that is amplified in some neuroblastoma tumors and cell lines, were assessed to further understand the molecular mechanisms leading to a reduction in tumor growth." (PMID 22662276, 2012). "MYCN is a well-known oncogene over-expressed in different human malignancies including neuroblastoma (NB), rhabdomyosarcoma, medulloblastoma, Wilms’ tumor, and small cell lung cancer." (PMID 23162796, 2012). "The identification of MYCN target genes enables a greater understanding of MYCN driven neuroblastoma tumorigenesis and promotes the identification of potential targets for therapeutic intervention in the treatment of neuroblastoma." (PMID 23226679, 2012). "Summary of studies which have shown increased SKP2 expression in the presence of MYCN and/or MYCN amplification in neuroblastoma." (PMID 23226679, 2012). "MYCN oncogene amplification is characteristic of human neuroblastomas, being found in 20% of these childhood cancers, and has been observed to be involved in breast tumorigenesis, with up-regulation being detected in inflammatory breast cancer." (PMID 22253826, 2012).
neuroblastoma (continued). "Our data show that AFS-PCR is a suitable method for quantification of MRD of tumor cells with ampGR and that it is not limited to neuroblastoma with MYCN-amplification." (PMID 23210797, 2012). "Twist-1 expression has been shown to be consistently overexpressed in MYCN amplified neuroblastoma tumors and cell lines, correlating with MYCN expression." (PMID 23226679, 2012). "The TH-MYCN transgenic neuroblastoma model, with targeted MYCN expression to the developing neural crest, has been used to study neuroblastoma development and evaluate novel targeted tumor therapies." (PMID 23284678, 2012). "This protein can be regulated by MYCN (v-myc myelocytomatosis viral related oncogene, neuroblastoma derived - avian) transcription factor in neuroblastoma." (PMID 22458888, 2012). "The transcription factor MycN is the prototypical neuroblastoma oncogene and a potential therapeutic target." (PMID 22619121, 2012). "MYCN has been reported to be targeted by miR-34a in neuroblastoma cells and somatic cell reprogramming." (PMID 22829753, 2012). "Additional copies of MYCN equal or less than 4-fold detected by FISH were considered as an MYCN gain, following a study on neuroblastoma." (PMID 22253826, 2012). "Similar to DKK3, DKK1 is also reported to be secreted in neuroblastoma cell lines, and downregulated indirectly by MYCN." (PMID 23226679, 2012). "BMI-1 is a direct transcriptional target of c-MYC and MYCN and is overexpressed in ~90% of neuroblastoma, correlating with MYCN expression." (PMID 23226679, 2012). "Despite its reduced levels, Galectin-3 can still exert residual antiapoptotic effects in MYCN amplified neuroblastoma cells, possibly due to its specific subcellular localization." (PMID 23152863, 2012). "A long-standing dilemma in neuroblastoma research is the proposed association between CASP8 methylation and MYCN amplification." (PMID 22984959, 2012). "MYCN is a proto-oncogene directly involved in neuroblastoma tumorigenesis, evident by the spontaneous development of neuroblastoma in a MYCN dose-dependent manner in transgenic murine models." (PMID 23226679, 2012). "Of these, ABC subfamily C member 1 (ABCC1), ABCC3, and ABCC4 are direct transcriptional targets of MYCN and expression levels of each of these genes are independent prognostic factors for neuroblastoma." (PMID 23267433, 2012). "In fact, other mechanisms have been suggested in other types of tumors, as CHD5 mutation or methylation is associated with KRAS or BRAF mutation in ovarian cancer, and CHD5 expression correlates with MYCN amplification in neuroblastoma." (PMID 22569290, 2012). "Here we discuss implications and caveats of exploiting this pathway and its connections to MYCN-induced DDR for a tailored therapy of MYCN-amplified neuroblastoma." (PMID 23091802, 2012). "In the analysis of MYCN-Amplified Neuroblastoma (NBL-MYCNA) our algorithm identified one of the most interesting current targets, CD276 (B7-H3)." (PMID 23251904, 2012). "The prevalence of MYCN amplification in neuroblastoma patients is 20–30% and the overall survival for these patients is 15–35%." (PMID 23284678, 2012). "ODC1, an oncogenic MYCN target, is rate-limiting for polyamine synthesis, and is overexpressed in many cancers including neuroblastoma." (PMID 23181218, 2012). "Of interest, it is worth mentioning that LY294002 has also been shown to destabilize MYCN in neuroblastoma." (PMID 23226679, 2012).